MET (MET proto-oncogene, receptor tyrosine kinase)
Diseases named in the same sentence as MET in open-access papers (continued):
Sharing a sentence is not in itself a finding about the gene and the disease.
melanoma (continued). "These factors include MET, a proto-oncogene often overexpressed in melanoma cells, which promotes cell growth." (PMID 26885752, 2016). "In conclusion, in patients with advanced solid tumors, the combination therapy demonstrated a manageable and predictable safety profile and preliminary signs of anticancer activity, particularly in patients with RCC, HCC, and melanoma with MET-high status." (PMID 25294187, 2015). "SOX10, PAX3, and MITF participate in regulation of MET (HGF receptor), which is expressed at high levels in human melanoma." (PMID 24743024, 2014). "MITF and PAX3 bind directly to the MET promoter; coexpression of these three proteins is found in melanoma biopsies." (PMID 24743024, 2014). "A skin cancer study revealed significant overexpression of c-MET in all skin cancers with stronger positive responce in malignant melanomas." (PMID 23251249, 2013). "Previous studies have demonstrated a significant MET overexpression in numerous tumor types including glioblastoma, melanoma, colorectal, breast, lung, gastric, thyroid and prostate cancer." (PMID 23251249, 2013). "Such mutations are rarely if ever seen in the HGF mouse melanoma model, which is probably a consequence of constitutive RAF activation downstream of the cell surface receptor for HGF, the MET tyrosine kinase." (PMID 22699362, 2013). "For instance, exosomes from highly metastatic melanoma cells increased the metastatic behavior of primary tumors by educating bone marrow progenitors through the receptor tyrosine kinase MET." (PMID 23439645, 2013). "Several recent publications have demonstrated the importance of HGF/MET signaling and the microenvironment in melanoma treatment resistance." (PMID 24025166, 2013). "A particularly striking recent example in this regard entails the ability of metastatic melanoma cells to emit exosomes containing high levels of the MET proto-oncogene." (PMID 23508692, 2013). "The c-MET protooncogene, which encodes hepatocyte growth factor receptor (HGFR), is highly expressed in human melanomas and linked to metastatic potential in melanomas." (PMID 22046555, 2011). "Ectopic expression of these miRNAs in primary melanoma cells showing a low level of endogenous miR-34b, miR-34c, and miR-199a* led to a decreased MET protein expression and resulted in the impairment of MET-mediated motility in these cells." (PMID 19638982, 2009). "Point mutations or gene fusions in other genes (e.g., mutations in BRAF, KRAS, APC, and MET genes, or gene fusions in ZEB2‐ALK and SOX5‐RAF1 genes) may be associated with melanoma proliferation or melanoma progression in satellite nevi or LCMN." (PMID 41474606, 2026). "Additionally, in a study, researchers designed a recognition circuit to identify melanoma cells by targeting both MET and MART1 antigens." (PMID 40308611, 2025). "Therefore, MET-expressing melanoma cells infiltrating the brain can benefit from the HGF-regulated systems that naturally occur in the brain and employ them as a survival strategy." (PMID 38386085, 2024). "The last receptor whose expression is increased in resistant melanoma cells is MET." (PMID 39175042, 2024). "Brain infiltrating melanoma cells hence may engage the HGF/MET signaling axis of brain cells and utilize it for regulation of survival and proliferation." (PMID 38386085, 2024). "MET has previously been identified as a biomarker for melanoma." (PMID 38353833, 2024). "The increasing trends of the average MACC1 and MET expression scores may suggest their role in melanoma development, progression and metastasis." (PMID 37496665, 2023). "To corroborate this finding, we also performed colocalization studies using fluorescent-labeled antibodies and a cell membrane marker; these immunofluorescence data show that MET and PD-L1 localize in close proximity on the surface cell membrane of melanoma cells." (PMID 37444518, 2023).
melanoma (continued). "Immunohistochemistry with the monoclonal MET-specific antibody was positive in the three cell lines, effectively validating this antibody for immunoprofiling of tissue sections from our cohort of canine melanoma samples." (PMID 37104404, 2023). "In the present study, we aim to investigate MACC1 and MET protein expression in melanocytic nevi, primary and metastatic human melanoma samples using immunohistochemistry, and further evaluating the prognostic value of MACC1 and MET, as well as their potential as biomarkers in melanoma." (PMID 37496665, 2023). "Similar to MACC1, MET expression in melanomas is significantly higher than in nevi (p=0.018)." (PMID 37496665, 2023). "It has been postulated that the interaction between MACC1 and MET signaling may be one of the mechanisms contributing to progression and metastasis of melanoma and other malignancies." (PMID 37496665, 2023). "Thus, selective MET inhibition is able to reduce the expression of PD-L1 in three out four melanoma cell lines." (PMID 37444518, 2023). "However, following oncogenic transformation, melanoma cells gain expression of HGF, allowing autocrine c-MET/HGF signalling that functionally decouples melanoma cells from keratinocytes, facilitating invasion and migration." (PMID 37181747, 2023). "We confirmed MET immunopositivity in canine malignant melanoma tissues in 63% of the specimens." (PMID 37104404, 2023). "To explore whether MET-targeted selective therapy can interfere with the modulation of PD-L1 expression induced by INF-γ in melanoma cells, we performed flow cytometry experiments on Crizotinib-treated cells." (PMID 37444518, 2023). "An indel mutation in HNF1A was identified in 29% of cases, and gain of function mutations in the MET oncogene were observed in 2 non-responding melanomas." (PMID 36248850, 2022). "It has been shown in melanoma cells that upregulation of c-MET could reduce the dependence on MAPK addiction and lead to MAPK inhibitor resistance." (PMID 36528667, 2022). "Besides, miR-34b, miR-34c, and miR-199a* have been shown to down-regulate MET expression, suppressing the invasive growth features in the melanoma cells." (PMID 33968718, 2021). "Finally, PAX3 (paired box gene 3 transcription factor) was shown, in conjunction with the transcription factor ETS1, to promote melanoma cells proliferation and metastasis by increasing the expression of MET, the HGF receptor." (PMID 35052351, 2021). "Moreover, the median expression level of MET transcript in MM was higher than that in mammary, ovarian, and prostatic adenocarcinomas or glioblastomas, but lower than in melanomas, thyroid carcinomas or papillary renal cell carcinoma." (PMID 34884673, 2021). "Furthermore, it has been reported that CAF-derived HGF can promote melanoma progression by enhancing melanoma cell proliferation via tyrosyl-phosphorylation of MET, MAPK and ERK2." (PMID 34067929, 2021). "The combination of vemurafenib and MET-targeting siRNA could inhibit cell growth and reduce cell invasion and migration by melanoma cells with MET amplification." (PMID 34638331, 2021). "As MET inhibition combined to sorafenib showed additive/synergistic effect in several cancers, a phase I trial was set to evaluate sorafenib and tivatinib combination in solid tumors with high MET activity including melanoma." (PMID 33918490, 2021). "HGF/MET autocrine activation is a well-known process in the development of malignant melanoma." (PMID 34885093, 2021). "The MET gene in melanoma is regulated by PAX3, SOX10 and MITF." (PMID 33807778, 2021). "Dysregulation of HGF and/or MET expression are both observed in several tumors including melanoma." (PMID 33918490, 2021). "MET protein was found overexpressed in melanoma and musculoskeletal tumors." (PMID 33918490, 2021). "Similarly, HGF activation of the MET signaling pathway can decrease the response of BRAF-mutant melanomas to BRAF inhibition." (PMID 34071428, 2021).
melanoma (continued). "Overexpression of KCNQ1OT1 contributed to the proliferation, migration, and invasion of melanoma and RB cells by sponging miR-153, and increasing MET proto-oncogene receptor tyrosine kinase (MET) and hypoxia-inducible factor-1α (HIF-1α) expression, respectively." (PMID 34827600, 2021). "Furthermore, skin melanoma is characterized by frequent amplifications of BRAF (7q34), NRAS (1p13.2), KIT (4q11) oncogenes (major mutated genes in melanoma) but also by EGFR (7p11.2) and MET (7q31.2) genes." (PMID 34885093, 2021). "It was indicated that MET (hepatocyte growth factor receptor), whose high level positively correlates with the more aggressive melanoma phenotype, promotes the activation of signaling pathways leading to the mobilization of neutrophils in response to cancer immunotherapies." (PMID 33171792, 2020). "Melanoma demonstrates relatively frequent MET aberrations, including MET gene amplification." (PMID 32659961, 2020). "Thus, based on our results showing that curcumol affected mouse melanoma B16 cell proliferation and invasion, we next investigated the effect of curcumol on c-MET, PI3K and Akt protein expression." (PMID 32194780, 2020). "Another study has established that MAPK pathway inhibition following BRAF inhibitor treatment induced rapid increases in MET and GAB1 expression and MET amplification was also observed to co-exist with BRAF hotspot mutations and represent the most common amplification among RTKs in melanomas." (PMID 32659961, 2020). "Finally, we found that curcumol inhibits c-MET expression and the downstream signaling pathway PI3k/Akt, and this inhibition effect of curcumol on mouse melanoma B16 cells can be reversed by miR-152-3p inhibitor." (PMID 32194780, 2020). "Inhibition of the c-MET pathway is a potential therapeutic strategy against melanoma 24,30,43,44." (PMID 32194780, 2020). "Based on these findings, we hypothesized that curcumol exerts anti-tumor activity, which may be associated with an increase in the level of miR-152-3p to decrease the c-MET in mouse melanoma B16 cells." (PMID 32194780, 2020). "MITF-mediated MET upregulation is known to elicit antiapoptotic effects in melanocytes and melanoma, while our earlier reports did show a GH-mediated increase in MET levels in human melanoma." (PMID 31547367, 2019). "For example, exosomes from melanoma could induce an increase of c-MET activation in cells derived from BM, thus reprogramming them toward a pro-angiogenic phenotype." (PMID 30642077, 2019). "Therefore, in this work we focused on the analysis of direct involvement of EGFR or MET in the regulation of invasiveness of melanoma cells derived from primary tumour and metastasis." (PMID 31638339, 2019). "MET (hepatocyte growth factor receptor) was also demonstrated to be connected with malignant skin cancer development, and the level of its expression seems to be related to the stage of malignancy in melanoma." (PMID 31649529, 2019). "The use of air CAP using μ-DBD and the SN can minimize the malignancy effects of melanoma cells by describing HGF/c-MET molecular mechanism of acting on G-361 human melanoma cells and in mice xenografts, possibly leading to suitable targets for innovative anti-melanoma approaches in the future." (PMID 31126298, 2019). "Interestingly, it has been demonstrated that combination of SU11274 and vemurafenib inhibited the growth of melanoma cells with constitutively activated c-MET more efficiently than SU11274 alone." (PMID 30513872, 2018). "HGF, c-MET and soluble MET (s-MET) are considered as biomarkers for melanoma, and they may provide a way to evaluate the response to therapy." (PMID 30513872, 2018). "Dissimilar to melanocytes, melanoma cells not only express c-MET, but also HGF." (PMID 30513872, 2018). "In many melanoma cases, EGFR and MET are overexpressed or upregulated as a result of gene mutation." (PMID 29719603, 2018).
melanoma (continued). "High c-MET expression in melanoma samples has also been correlated with a poor clinical outcome." (PMID 30513872, 2018). "Furthermore, the activation of HGF receptor, MET, in bone marrow stromal cells by melanoma cells is associated with metastasis." (PMID 29642534, 2018). "Taking advantage of the in vivo study of EXs derived from B16-F10 cells injected in mice, Peinado and collaborators demonstrated that melanoma EXs could educate bone marrow progenitor cells toward a pro-metastatic phenotype through MET signaling." (PMID 29534457, 2018). "Next, we decided to examine the proapoptotic effect of EGFR and MET inhibitors on melanoma cells." (PMID 29719603, 2018). "However, strong MYSM1-binding to a fragment of the c-MET promoter close to the TSS was detectable in A375 melanoma cells." (PMID 28978033, 2017). "The HGF/SF model may not be appropriate for testing of inhibitors of mutant BRAF, the constitutive MET activity and consequent downstream activation of BRAF in HGF/SF melanomas likely precludes the genesis of BRAF-activating mutations." (PMID 28788083, 2017). "Both, c-MET as well as PAX3, have previously been implicated in melanoma cell survival." (PMID 28978033, 2017). "In addition, constitutive expression of HGF/SF results in activation of the receptor tyrosine kinase and proto-oncogene MET, a growth-promoting autocrine loop characteristic of many human melanomas." (PMID 28788083, 2017). "Moreover, there was very high RNA levels of the HGF-receptor MET on all four melanoma cells and exhibited a dose dependent rise with added hGH." (PMID 28223541, 2017). "Interestingly, MET activation has been identified as a mechanism of resistance to BRAF inhibition in melanoma." (PMID 28103611, 2017). "MET fusions occurred in tumors that ranged from benign to malignant, and this finding strongly suggests that MET fusion kinases represent an early event during melanoma progression." (PMID 29156643, 2017). "Moreover, MYSM1 was highly expressed and co-localized with PAX3 and c-MET in melanoma cells in culture and in SSM samples in situ." (PMID 28978033, 2017). "Possible co-operators in melanoma development include MET and CDKN2A." (PMID 27439913, 2016). "They found that the MET-activated signaling proteins are expressed in highly metastatic melanoma derived exosomes and that the transfer of the exosomal receptor tyrosine kinase MET from tumor-derived exosomes to BM progenitor cells promotes the metastatic process in vivo." (PMID 26583135, 2015). "Mutations in MET have not been described in melanoma, but there is strong evidence that this RTK is involved in melanoma growth and metastases (see below: WNT pathway and HGF expression in stroma)." (PMID 24743024, 2014). "BRAF inhibitor resistance could be caused by HGF-triggered MET activation, and IGF-1 triggered its receptor activation in BRAF mutant melanoma." (PMID 24952482, 2014). "They identified that the MET-activated signaling proteins are expressed in highly metastatic melanoma derived-exosomes and that the transfer of the exosomal receptor tyrosine kinase MET from tumor derived-exosomes to bone marrow progenitor cells promotes the metastic process in vivo." (PMID 23466882, 2013). "Interestingly, an avid uptake of MET by myeloid cells is not only observed in experimental settings, but also occurred in stage IV melanoma, as indicated by the high levels of MET staining on the surface of the circulating BMDCs in these patients." (PMID 23508692, 2013). "Therefore, metastatic melanoma cells expressing MET might scavenge HGF from the brain for activation of processes downstream of MET mediating survival and proliferation." (PMID 38386085, 2024). "Of note, most co-occurring mutations in melanoma BRAF Class 2 and 3 (KMT2A, NOTCH1, APC) are of unknown significance, whereas those in Class 1 are amplifications and putative drivers such as NOTCH2 and MET amplifications." (PMID 38275886, 2024).
melanoma (continued). "Additionally, previous studies reported that other genes are frequently mutated in melanoma and other cancer types, including BRCA2 (9/112, 8%), LRP1B (9/112, 8%), MET (8/112, 7%), PRKDC (7/112, 6%), NOTCH4 (7/112, 6%), CCND3 (6/112, 5%), and FGF3/4/19 (6/112, 5%)." (PMID 37649078, 2023). "Additionally, c-MET oncoprotein on melanoma cell-derived exosomes educates BMDCs toward a pro-vasculogenic and pro-metastatic phenotype and c-MET-low melanoma cells can upregulate c-MET to adapt to its needs, like facilitate metastasis, because it gives cells invasion and motility capacity." (PMID 37022605, 2023). "Subsequent analysis of selected proteins in sEVs of stage I, stage III, stage IV melanoma patients and healthy controls revealed a potential diagnostic “signature”, which included the melanoma-specific protein TYRP2, VLA-4, HSP70, an isoform of HSP90 and oncoprotein MET." (PMID 35804857, 2022). "It should be noted that c-MET (tyrosine kinase receptor) may be overactivated in the event of the excessive secretion of its HGF ligand produced by tumour cells or the tumour microenvironment of melanoma." (PMID 34203771, 2021). "Another combination of afatinib with crizotinib (a MET inhibitor) showed efficacy, was proposed as a promising alternative targeted therapy option for melanoma irrespective of BRAF/NRAS mutational status, and may overcome resistance to BRAF inhibitors." (PMID 33918490, 2021). "Several studies have investigated the role of EVs secreted from normoxic melanoma cells and have shown that such EVs are involved in therapy resistance as well as in metastasis by colonising the lymph nodes or by educating the pro-metastatic phenotype through the receptor tyrosine kinase MET." (PMID 32183388, 2020). "In addition, TEX could also transfer the oncogene MET from melanoma cells to BM progenitor cells and thereby promote metastasis." (PMID 29720982, 2018). "Thus, in melanoma, one sample (6.2%) had an uncommon BRAF (c.1400C>T; p.Ser467Leu) mutation, one (6.2%) had an NRAS (c.385C>T; p.Gln129*) mutation, and rare EGFR, ERBB2, KRAS, and MET mutations were also exhibited in one sample (6.2%)." (PMID 28404952, 2017). "To demonstrate that upregulation of EPHA2 and MET also occurs in tumors of patients who develop resistance to BRAFi therapy we have analyzed tumor samples obtained before treatment and after progression in three melanoma patients receiving treatment with BRAFi." (PMID 29048432, 2017). "Indeed, we recently showed that melanoma-secreted exosomes transfer information and reprogram bone marrow progenitor cells toward a pro-vasculogenic phenotype in the premetastatic niche, acting through the receptor tyrosine kinase, MET." (PMID 25759690, 2015). "Indeed, dual blockade of MEK/BRAFV600E (with PD184352, PLX4720 or vemurafenib) and MET (with crizotinib, SU11274 or MET-specific siRNA) resulted in reversal of drug resistance and reduced the proliferation of melanoma cell lines, which was restored by exogenous HGF." (PMID 24920406, 2014). "They analyzed the enriched gene of NRAS‐mutant melanoma cell lines, and the results showed that the overexpression of Axl, c‐KIT, and c‐MET, which as the target for amuvatinib." (PMID 41492362, 2026). "Chromosome 7, with frequent copy number gains in all four cancers, harbors several key oncogenes such as EGFR, CDK6, and MET in glioma; KMT2C and PMS2 in medulloblastoma; BRAF, RAC1, and TRRAP in melanoma." (PMID 41537310, 2026). "SOX family members are common PAX protein co-factors; in melanocytes and melanoma, PAX3 interacts with SOX10 and drives a number of downstream genes, such as MITF, MET, and RET." (PMID 40428399, 2025). "Studies on MACC1 expression and its functional roles in melanoma are sparse, despite the known mechanistic link between MACC1 and HGF/MET signaling and their critical roles in inducing metastasis." (PMID 37496665, 2023).